IL17A (interleukin 17A)
Diseases named in the same sentence as IL17A in open-access papers (continued):
Sharing a sentence is not in itself a finding about the gene and the disease.
tumor (continued). "However, IL-17a has different promotion effects on tumor angiogenesis." (PMID 32522267, 2020). "Finally, we wanted to evaluate whether the blockade of TGF-β-signaling in IL-17A+ CD4+ T cells would also impact tumor development." (PMID 32451418, 2020). "Taking into account the propensity of IL-17A to propel tumor growth either in an autocrine or paracrine fashion, findings on IL-17D suggest that this cytokine counterbalances the pro-tumor activity of Th17 cells and IL-17A, and strategies to increase IL-17D might find clinical application." (PMID 33244315, 2020). "Thus, TNBC cells, at least some of them, are fully able to produce pro-inflammatory cytokine IL-17A, which may play a key role in creating a unique tumor microenvironment in TNBC patietns." (PMID 32770025, 2020). "Therefore, we believe the primary action of tumor-derived IL-17A in tumor-bearing mice is to induce a rapid expansion of myeloid cells, including neutrophils and MDSCs, via the production of STAT3-activating cytokines including IL-6, G-CSF, and GM-CSF by tumor cells." (PMID 32770025, 2020). "However, it remains unclear how tumor-derived IL-17A may shape tumor microenvironment, control anti-tumor immunity, and influence the course of tumor development and tumor progression." (PMID 32770025, 2020). "Thus, our results suggested that IL-17A was dominantly produced in tumor-infiltrating γδ T cells of OC, which may indicate the suppressive roles that IL-17A plays in the OC microenvironment." (PMID 31064389, 2019). "Moreover, in vitro re-stimulation of TDLN cells with ovalbumin (OVA) showed increased proportion of IL-17+ CD4+ T cells in Tmem176b−/− compared with WT mice, and in vivo IL-17A blockade showed a clear trend toward suppression of the antitumor effect in tumor-bearing Tmem176b−/− mice." (PMID 31085177, 2019). "Serum IL17A level is positively linked to vascular endothelial growth factor (VEGF) concentration in NSCLC patients, suggesting IL17A may promote angiogenesis in the tumor." (PMID 31921642, 2019). "Therefore, we investigated the levels of IFN-γ and IL-17A secreted by γδ T cells in PB and tissues, and found higher levels of IL-17Ain both PB and tissues of OC patients, but lower levels of IFN-γ secreted by γδ T cells, while IL-17A was inclined to infiltrate the tumor milieu of OC." (PMID 31064389, 2019). "However, CD8+ T cells depletion did not restore the tumor growth in both IL17A sufficient and deficient conditions, suggesting Gr1+ CD11b+ myeloid cell can directly promote tumor growth." (PMID 31921642, 2019). "Further investigation of the effects of IgE antibodies on the expression of additional soluble mediators such as IL-17A, and other family members, and IL-37, reported to influence macrophage phenotype, may shed light into the impact of IgE-FcεRs interactions in the tumour microenvironment." (PMID 30956175, 2019). "Neutrophils in the tumor microenvironment may be the main source of IL-17a." (PMID 30616627, 2019). "Emergence of certain myeloid subsets in the spleen, such as CD44+MDSCs and IL-17A+MDSC were associated with advanced cancer, while within the lymphoid subsets, the absence the B220+ B-cells, CD62L+ B-cells, CD62L+CD4+ T-cells, and CD62L+ CD8+ T-cells was shown in the untreated tumor bearing mice." (PMID 31881770, 2019). "In addition, VEGF was down regulated when inhibiting IL-17A in tumor tissue." (PMID 30800130, 2019). "In addition to the immunosuppressive cytokines, pro-inflammatory cytokines including IL-17A often promote tumor growth and may be produced at higher levels when intratumoral T cells are dominated by the Vδ1 subset." (PMID 29937769, 2018). "Moreover, administration of recombinant mouse IL-17A reversed the anti-tumor effects of SBE." (PMID 28086772, 2017). "Interestingly, IL-17A can promote tumor growth through an IL-6/STAT-3 signaling pathway." (PMID 28402963, 2017).
tumor (continued). "In addition to IL-6, the increase of IL-35 expression in tumor could increase IL-17A and G-CSF in blood and tumor microenvironment." (PMID 28432279, 2017). "Recombinant IL-17A administration could reverse the anti-tumor effect of SBE, and the volume of tumors of SBE combined with IL-17A treatment group was significantly larger than SBE treatment group (P < 0.05), and significantly smaller than vehicle control group (P < 0.05)." (PMID 28086772, 2017). "However, IL-17A enhances cytotoxic T lymphocytes response resulting in tumor suppression." (PMID 28035060, 2017). "Similarly, antiangiogenic therapies might fail due to the IL-17A-driven emergence of resistant tumor stromal cells." (PMID 28492497, 2017). "Therefore, exploring the role of IL-17A in TSCC and its underlying mechanisms would be useful to understand the crosstalk between TSCC cells and tumor microenvironment, shedding new insights on TSCC prevention and treatment by targeting critical immuno-modulatory cytokine." (PMID 28035060, 2017). "Therefore, we assessed whether IL-17A promotes PDL1 expression in tumor cells and whether targeting of IL-17A could inhibit ER-negative breast cancer progression in a murine model." (PMID 27935862, 2017). "Thus, besides IL-17A, IL-17B also could play an important role in tumor progression through its binding to IL-17RB and might represent a potential therapeutic target in solid tumors, such as breast and pancreatic cancers." (PMID 29371916, 2017). "Furthermore, IL-17A in tumor tissue positively correlated with TNM stage." (PMID 29029520, 2017). "In addition, IL-17A may be involved in immunomodulation by suppressing immune-related cells, which play a role in inhibiting anti-tumor immunity." (PMID 28406993, 2017). "Interestingly, we observed several pro-inflammatory cytokines such as IL-17A, IL-6 and TNF-α that were downregulated (at an mRNA level) in mda-9-deficient naïve lungs, suggesting a potential impairment of pro-tumorigenic responses to invading tumor cells." (PMID 27341128, 2016). "Since the decrease of small tumor numbers (31%) was less potent than that of large tumors (55%), it could be noted that the role of IL-17A from Apc/Min+ Tregs is more important for large tumor formation in IL-17A-mediated tumor microenvironment." (PMID 26146642, 2015). "However, IL17A has been reported to stimulate angiogenesis in tumor." (PMID 26083022, 2015). "Since we observed that the level of SDF-1 was significantly reduced with anti-IL-17A antibody treatment, we conducted an in vitro trans-well Boyden chamber assay with the bone or lung lysate in the bottom chamber and the 4 T1 or PyV MT tumor cells in the top chamber." (PMID 24674692, 2014). "However, IL-17A was significantly increased in draining lymph nodes of the irradiated group, compared to IL-6 and its expression exhibited a correlation with enhanced tumor growth." (PMID 25181290, 2014). "However, further studies are needed to determine whether blocking IL-17A helps in preventing recurrence of both the primary irradiated tumor and recurrence in low-dose normal livers." (PMID 25181290, 2014). "Therefore, we further examined whether IL-17A neutralization can rescue accelerated tumor growth in pre-irradiated beds." (PMID 25181290, 2014). "Therefore, irradiating tumor beds might enhance the growth of subsequently implanted tumors via IL-17A." (PMID 25181290, 2014). "Therefore, IL-17A might be a major factor for enhancing tumor growth in low-dose pre-irradiated tumor beds." (PMID 25181290, 2014). "In addition, VEGF was down regulated by inhibiting of IL-17A in tumor tissues (P<0.05)." (PMID 23372655, 2013). "However, overexpression models may be artificial, because these cells could produce much higher levels of IL-17A than those in a general tumor microenvironment." (PMID 23372655, 2013). "Interestingly, systemic pretreatment of animals with murine IL-17A exacerbated tumor growth." (PMID 24454480, 2013).
tumor (continued). "At the same time, IL-17A could further promote IL-23 expression in HCC tumor cells." (PMID 23050001, 2012). "Yet IL-17A could promote tumor growth in conjunction with IL-6-dependent activation of Stat3." (PMID 22855687, 2012). "Similarly, IL-17A has been found to elicit pro- as well as anti-tumor properties." (PMID 22855687, 2012). "Nevertheless, there is growing evidence that IL-17A could rather act as a tumor promoter." (PMID 22855687, 2012). "Interestingly, IL-17A production by T cells was negatively correlated with tumor burden." (PMID 21949734, 2011). "Inhibiting BTNL2 reduces the number of IL-17A+ γδ T cells, increases the presence of cytotoxic CD8+ T cells, and slows tumor progression." (PMID 40536951, 2026). "In vivo, IL-17A blockade reduces CTC survival and tumor angiogenesis (CD34 expression), shifting immunity toward TGF-β1 dominance and fewer CD8+ cells." (PMID 41596231, 2026). "By screening differentially expressed cytokines in LX2 cells activated by various tumor cells, we found that the expression of CSF2, IL33, COX2, and IL17A was upregulated." (PMID 41214328, 2025). "Studies indicate that CXCL5 induction is driven by IL-17A or IL1 in the TME, endowing tumor cells with an invasive phenotype." (PMID 39670859, 2025). "Collectively, these findings reveal that IL17A and IL26 not only individually enhance malignant phenotypes of GC cells but also act synergistically to potentiate tumor progression." (PMID 40452847, 2025). "When we observed that KPC/IL17A−/− tumours were much more infiltrated by CD8+ T cells and significantly less by Treg, we thought to exploit the TME reshaping mediated by the IL17A's depletion to improve the ENO1‐DNA vaccine efficacy." (PMID 40831074, 2025). "The anti-tumor efficacy of antibiotics primarily depends on the reduction of IL-17A, this depletion results in an increase in anti-tumor T cells secreting IFN-γ within the tumor microenvironment and a decrease in pro-tumor T cells producing IL-17A and IL-10." (PMID 41403642, 2025). "This analysis highlighted the consistent induction of pro-inflammatory cytokines such as IL-1β, IL-6, IL-8, IL-10, IL-17A/F, and TNF, which are known to play central roles in immune activation, macrophage polarization, and tumor–immune cell crosstalk." (PMID 41514627, 2025). "infection led to an increase in IL-17A+ CD4+ T cells and γδ T cells, both involved in chronic inflammation and tumour progression." (PMID 40278081, 2025). "In our study, we observed a slight increase in the expression of IL-17A, IL-6, and CXCL13 following PD-1 signaling activation, and no inhibitory effect on IFN-γ and TNF-α, which are downregulated in tumor T cells." (PMID 40825269, 2025). "In contrast, live C. albicans infection in oral cancer induces IL-17A/IL-17RA-driven M2-like TAM polarization, characterized by up-regulation of immune checkpoints such as PD-L1 and Galectin-9, ultimately accelerating tumor progression." (PMID 41355895, 2025). "This pathogen-driven macrophage activation is further potentiated by elevated levels of proinflammatory cytokines such as IL-17A and TNF-α, which together foster a tumor-promoting microenvironment." (PMID 41355895, 2025). "Numerous studies have reported significant associations between the expression levels of inflammatory cytokines—including IL-6, CXCL9, TNF-α, IL-17A, and IL-32—and LUAD tumor stage, metastasis, and prognosis." (PMID 40136462, 2025). "Next, HPV-specific CD8+ and CD4+ T cells participate in dendritic cell recruitment and tumor inflammation through the production of pro-inflammatory cytokines, such as TNF-α, IFN-γ, and IL-17A." (PMID 40141426, 2025). "Specifically, alterations in cytokines such as IL32, IL22, IL17F, IL17A, IL16, IL15, and HMGB1 can create an immunosuppressive tumor microenvironment in CTCLs to facilitate immune evasion and tumor progression." (PMID 39409988, 2024).
tumor (continued). "Pretreatment of a mesothelial cell monolayer with TNF enhanced the adhesion of tumor cells, with clear further enhancement by combined TNF/IL‐17A treatment." (PMID 38566518, 2024). "Given the increase in pro-inflammatory CD4(+) T cells after oHSV treatment, we next analyzed IFN-γ, TNF-α, IL-4, IL-17A, and IL-21 intracellular expression within the CD4(+) tumor infiltrates." (PMID 38895115, 2024). "It was also observed that the combined administration of IL-17A monoclonal antibodies and anti-PD-L1 monoclonal antibodies significantly increased therapeutic efficacy by reducing PD-L1 expression in NSCLC tumor tissue." (PMID 39906741, 2024). "Tumours with positive PD-L1 TPS, IC, or CPS expression were more likely to have low IL-17A+CD4+ T cell infiltration in the tumour stroma." (PMID 39409156, 2024). "The IL-17A and VEGF loop can also induce TGF-β expression by immunosuppressive and tumor cells, stimulating VEGF receptors on endothelial cells, angiogenesis, tumor growth, and metastasis." (PMID 38515019, 2024). "DTIC suppressed more efficiently pro‐inflammatory cytokines (IL‐17A, IL‐8) and immune‐modulatory cytokines (INF‐α2, IL‐13) that promote tumor growth or immune evasion." (PMID 39475010, 2024). "IL17A augments IL6 production by activating tumor-intrinsic STAT3, resulting in tumor growth and invasion." (PMID 38672199, 2024). "We therefore subsequently discuss our findings with a focus on IL‐17A, its synergism with TNF and the promotion of tumor cell adhesion to the mesothelium." (PMID 38566518, 2024). "Significant correlations between PD-L1+ lymphocytes and tumour-infiltrating CD4+, Foxp3+CD4+, IL-17A+CD4+ T cells and M2 macrophages were found." (PMID 39409156, 2024). "Secondly, IL-17A inhibits CD4+ and CD8+ T cell infiltration in some tumor types and promotes infiltration of immune cells that exhibit immunosuppressive functions, like regulatory T cells and myeloid-derived suppressor cells." (PMID 39411241, 2024). "Previous studies have reported that infiltrated macrophages, endothelial cells, fibroblasts, and even tumor cells in the TME can be the main sources of IL-17A and IL-17 F." (PMID 38515019, 2024). "Other cytokines, such as IL-17A, TNF-α, and IL-6, activate NF-kappa β and signal transducer and activator of transcription 3 (STAT3), inducing tumor growth." (PMID 39456655, 2024). "Tumor-infiltrating MAIT cells presented an exhausted phenotype featuring upregulated PD-1 and IL-17A and downregulated IFN-γ." (PMID 39802954, 2024). "Compared with the tumor group, CUMS significantly decreased HDC and HIS levels and increased IL-6, IL-17A, NE, COR, and 5-HT levels." (PMID 39720595, 2024). "Yet, SSCs were reported to recruit γδT cells producing either IL‐17A or IFN‐γ, depending on the tumor stage." (PMID 38273461, 2024). "Peripheral circulating, tumor-adjacent PMNs and TANs expressed similarly low levels of proangiogenic VEGF and IL-17A in early and advanced disease." (PMID 38329810, 2024). "The findings disclosed a significant difference in the serum and tissue concentrations of IL-17A, VEGF, and TGF-β between the patient and the control groups, as well as tumor and normal tissues." (PMID 38515019, 2024). "TNF has also been reported to upregulate IL‐17A production by CD4+ T cells, thereby recruiting myeloid cells into the TME and enhancing tumor growth." (PMID 38566518, 2024). "Tumours with positive PD-L1 IC expression were more likely to have high Foxp3+CD4+ T cell infiltration in tumour islets, as well as tumours with positive PD-L1 TPS, IC, or CPS were more likely to have low IL-17A+CD4+ T cell infiltration in the tumour stroma." (PMID 39409156, 2024). "Studies have revealed that the IL-17A/IL-17RA signaling pathway is activated in oral cancer cells infected with Candida albicans, which induces CCL2 and attracts macrophages into the tumor environment." (PMID 39906741, 2024).
tumor (continued). "To our knowledge, we are the first who evaluated PD-L1+ lymphocyte distribution in tumour tissue in the context of the TME (CD4+ T cells, Foxp3+CD4+ T cells, IL17A+CD4+ T cells, CD8+ T cells, M1 and M2 macrophages)." (PMID 39409156, 2024). "Furthermore, IL-17A could increase PD-L1 expression and facilitate tumor immune evasion." (PMID 39802954, 2024). "Meanwhile, IL17A+CD4+ T cells in tumour tissue were of less interest, and there is no data representing the effect of these cells, depending on their compartment of tumour tissue." (PMID 39409156, 2024). "IL-17A indirectly attracts CD4+ and CD8+ T cells to tumor sites and enhances natural killer cell activity." (PMID 39411241, 2024). "Decrease IL-17A levels, increase IFN-γ release, increase CD8 infiltration and showed durable tumor stabilization efficacy in mCRC patients." (PMID 37020871, 2023). "In the GEO datasets and the tissue homogenates, we found a positive correlation between the tumor concentrations of YKL-40 and IL-17a." (PMID 37185706, 2023). "When the host immunity of C57 mice was compromised by knocking down the Ifng gene or the Il17a/Il17f genes in the mice, the growth of EO771 tumor at the primary site accelerated." (PMID 37553342, 2023). "The expression of YKL-40 was significantly higher in CRC tumor tissue compared to healthy tissue and correlated with MMP-8, IL17A, and PD-L1 expression." (PMID 37185706, 2023). "We have previously shown that NKG2D ligands are highly expressed in that model and that similarly, NKG2D-expressing γδT cells that secrete IL-17A accumulate in the TME, contributing to a pro-tumorigenic microenvironment that sustains tumor growth." (PMID 36980678, 2023). "MiR-4508 activated fibroblasts to form PMNs in the lung and promoted metastatic tumor growth by depleting its target, RFX1, to trigger the IL17A-p38 MAPK-NF-κB signaling pathway." (PMID 37781522, 2023). "The interaction with MR-1 expressed on tumor cells and TIME MAIT cells activate them to release IL-17A, suppressing cytotoxic T and NK cells." (PMID 37508372, 2023). "Out of the six members of the IL17 family of cytokines, IL17A, IL17B, and IL17E have been found to aid in tumor growth, angiogenesis, metastasis, and chemoresistance." (PMID 37503343, 2023). "Specifically, in the Apcmin/+ model of intestinal tumorigenesis, we demonstrated a role for NKG2D in IL-17A-producing γδT cells, a particular subset defined as CD27-Vγ6 T cells with pro-tumor function." (PMID 36980678, 2023). "IM can promote tumor growth in mice by regulating immune responses, such as increasing interferon gamma (IFN-γ)-producing T cells and decreasing interleukin 17a (IL-17a)- and IL-10-producing T cells." (PMID 37009513, 2023). "IL-17A stimulation reduced LFA-1 surface expression on stem-like exhausted CTLs and the counterpart ICAM-1 (intracellular adhesion molecule-1) on tumor vascular endothelium." (PMID 37605139, 2023). "PAR1CAR-T cells secrete proinflammatory cytokines and chemokines, including TNF-α, IFN-γ, IL-1α, IL-4, IL-6, IL-17A, and GRO, upon encountering PAR1 antigens that exhibit potent cytolytic capacities against PAR1-expressing tumor cells." (PMID 37667257, 2023). "This study attempted to determine the impacts of IL-17A on EGFR-mediated tumor proliferation and responses to EGFR-TKI treatment in LUAD, and to further investigate the mechanisms involved in the crosstalk between IL-17A and EGFR signaling." (PMID 37444399, 2023). "The proinflammatory cytokine, interleukin (IL)-17A, and IL-17A-producing cells were reported to be elevated in the tumor microenvironment and peripheral blood of NSCLC patients and to be correlated with tumor progression and poor prognoses." (PMID 37444399, 2023). "In conclusion, our results show that IL-17A promotes NSCLC cell proliferation and increases PD-L1 expression in tumor cells by reducing PD-L1 degradation through inhibition of autophagy, creating a suppressive immune microenvironment." (PMID 37978543, 2023).